DRAIC (downregulated RNA in cancer, inhibitor of cell invasion and migration)
Synonyms: C15orf50; LINC00593; PCAT29
Gene: Long non-coding RNA gene on chromosome 15 (69,462,921 to 69,855,357, forward strand). Ensembl gene ENSG00000245750.
Diseases named in the same sentence as DRAIC in open-access papers:
DRAIC is named in the same sentence as 36 diseases in open-access papers, as found by Europe PMC text mining. Sharing a sentence is not in itself a finding about the gene and the disease. The quoted sentences say what the papers report.
prostate carcinoma (16 papers, 2016 to 2025). A carcinoma that arises from epithelial cells of the prostate gland. "Consistently, DRAIC has been shown to inhibit migration and proliferation, albeit in prostate cancer cells." (PMID 39410631, 2024). "Since we showed in our cell fractionation assay that DRAIC was predominantly expressed in the cytoplasm of prostate cancer cells, several molecular mechanisms as a cytoplasmic lncRNA have been reported." (PMID 38075206, 2024). "Accumulating evidence has reported that the differential expression of DRAIC in prostate cancer, lung cancer, glioma, breast cancer, colorectal cancer, esophageal cancer, gastric cancer, nasopharyngeal carcinoma, and retinoblastoma." (PMID 35992823, 2022). "lncRNA DRAIC was first discovered to act as a tumor suppressor in prostate cancer, but it appears to exert varied biological activity in different diseases." (PMID 35992823, 2022). "In prostate cancer, DRAIC binds to IKK subunits to block interunit binding and inhibit NF-κB activation, thereby inhibiting invasion and proliferation of cancer cells." (PMID 34306024, 2021). "As for DRAIC, it was reported inhibiting prostate cancer progression through suppression of NF-κB activation." (PMID 33771173, 2021). "The lncRNA DRAIC was first identified in prostate cancer cell lines and showed higher expression in human LNCaP cells (which is androgen-dependent) compared with LNCaP-derived C4-2B cells (which is androgen independent)." (PMID 30544991, 2018). "It was also found DRAIC expression was upregulated in IR-resistant PCs through expression analyses of human prostate cancer xenografts with predetermined radioresistant/sensitive phenotypes." (PMID 30544991, 2018). "In prostate cancer, plenty of LncRNAs, including PCGEM1, SOCS2-AS1, PlncRNA-1, CTBP1-AS, DRAIC and PCAT29, have been reported to be associated with AR pathway, and thus act as regulators in the development of PCa." (PMID 28771526, 2017). "In addition, in prostate cancer, lncRNA DRAIC can bind to IKK and reduce its kinase activity on IkB, which inhibits the activation of NF-κB, thereby inhibiting the proliferation and metastasis of prostate cancer cells." (PMID 34123804, 2021). "DRAIC could inhibit the progression of prostate cancer and gastric cancer, facilitate the proliferation and migration of nasopharyngeal carcinoma and regulate autophagic flux." (PMID 34163531, 2021). "Previously, we identified a novel tumor-suppressive lncRNA, DRAIC (Downregulated RNA in cancer, inhibition of cell invasion and migration), which is a 1.7 kb spliced and polyadenylated RNA that was predominantly expressed in the cytoplasm of prostate cancer cell lines." (PMID 38075206, 2024). "These include genes such as DANCR, DRAIC, PCAT29, PCAT19, and PCAT14, all of which have been shown to be regulated by the AR, and are important regulators of prostate cancer cell proliferation, division, migration, and invasion." (PMID 38396008, 2024). "Subsequently, DRAIC was revealed to interact with subunits of the IκB kinase (IKK) complex to inhibit NF-κB activity and suppress prostate cancer progression." (PMID 38075206, 2024). "DRAIC was shown to positively regulate FOXA1 and NKX3-1 and to block the transformation of LNCaP prostate cancer cuboidal epithelial cells to a fibroblast-like morphology." (PMID 35992823, 2022). "DRAIC (also known as LOC145837 and RP11-279F6.1), is a long non-coding RNA associated with several types of cancer including prostate cancer, lung cancer, and breast cancer." (PMID 30544991, 2018).
lung carcinoma (7 papers, 2018 to 2024). "We demonstrate that low expression of DRAIC is consistently associated with poor overall survival outcomes for lung cancer patients, highlighting the importance of lncRNA-signalling networks." (PMID 39410631, 2024). "Our recent findings based on in silico analysis revealed that a higher expression of DRAIC is associated with the neuroendocrine (NE) feature in lung cancer." (PMID 38075206, 2024). "To investigate the biological processes associated with dysregulation of DRAIC in lung cancer, we applied gene ontology analysis to the sets of DE genes (LUSC and LUAD, independently)." (PMID 39410631, 2024). "Of particular significance is that matched low expression of DRAIC and SBK1 mRNAs was associated with poor survival in both lung cancer types." (PMID 39410631, 2024). "DRAIC, which is a crucial part of this network, has been shown to play a role in lung cancer progression." (PMID 39410631, 2024). "In summary, we show for the first time the pan-lung cancer prognostic role of DRAIC downregulation, potentially through dysregulated miR-92a-1-5p and the corresponding downregulation of SBK1." (PMID 39410631, 2024). "Numerous reports have shown that lncRNA DRAIC is abnormally expressed in PCa, lung cancer, glioma, breast cancer, colorectal cancer, esophageal cancer, gastric cancer, nasopharyngeal carcinoma, retinoblastoma, HSRC, and omphalocele." (PMID 35992823, 2022). "DRAIC expression slowed Y79 cell growth compared to controls, in support of previous data from lung cancer, showing that reducing the expression of DRAIC back to physiological levels changes the proliferation potential of cells." (PMID 31058073, 2019). "Given that our previous results suggest that DRAIC might act as a tumour inhibitor in lung cancer, the correlations between DRAIC, clinical data, and immune infiltration were investigated to further validate our observations." (PMID 39410631, 2024). "The ceRNA interactions of DRAIC suggest that low expression of this lncRNA may modulate these networks to promote lung cancer progression." (PMID 39410631, 2024). "Moreover, we found that the majority of the consistently altered mRNAs in the DRAIC expression group were downregulated, further suggesting that the deregulation of DRAIC ceRNA networks plays a role in the progression of lung cancer." (PMID 39410631, 2024). "The finding of this bioinformatics analysis suggests that targeting DRAIC ceRNA may hold both prognostic and therapeutic utility in lung cancer management." (PMID 39410631, 2024). "Because CISH detected the DRAIC signal in a subset of NECa and SCLC (NE-differentiated lung carcinoma), we hypothesized that DRAIC may perform a biological role in NECa." (PMID 38075206, 2024). "We identified other mRNA targets of DRAIC, which may contribute to lung cancer progression." (PMID 39410631, 2024).
breast carcinoma (6 papers, 2018 to 2024). "Survival analysis considering all patients with breast cancer revealed high expression of DRAIC was significantly associated with poor overall survival." (PMID 30544991, 2018). "lncRNA DRAIC expression was distinctly upregulated in 828 breast cancer specimens and cell lines (HeLa, T47D, MCF-7, SKBR3, MDA-MB-361, and MDA-MB-231 cells)." (PMID 35992823, 2022). "And lncRNA DRAIC was activated by FOXP3 in breast cancer and promoted cell proliferation in SKBR3 and MDA-MB-231 cells via sponging miR-432-5p to increase SLBP levels." (PMID 35992823, 2022). "lncRNA DRAIC was overexpressed at a higher level in high malignancy breast cancers when compared to low malignancy cases, suggesting its diagnostic and prognostic value." (PMID 35992823, 2022). "Although the anti-cancer effects of DRAIC have been verified by some studies, there were still several sources of evidence that DRAIC also plays an oncogenic role in other cancers such as breast cancer (BC) and nasopharyngeal carcinoma (NPC)." (PMID 32351584, 2020). "We found that higher DRAIC expression in breast cancer significantly negatively correlates with immune cell infiltration especially dendritic cells and neutrophils." (PMID 30544991, 2018). "We also found one report regarding breast cancer cell lines showing that DRAIC expression is higher in lapatinib sensitive breast cancer cell lines compared to Lap resistant cell lines." (PMID 30544991, 2018). "In conclusion, DRAIC expression was found to be higher in breast cancer patients, especially in ER, PR, and HER2 positive patients." (PMID 30544991, 2018). "In breast cancer, DRAIC expression was identified as a potential onco-lncRNA based on its elevated expression in tumor tissues compared to the adjacent normal tissues." (PMID 30544991, 2018). "High expression of DRAIC in breast cancer tissues compared to normal breast tissues was validated in the present study, confirming its role as a potential onco-lncRNA in breast cancer." (PMID 30544991, 2018). "In breast cancer, Lee reported that DRAIC was a potential oncogene and using more than 100 breast cancer cell lines they showed that DRAIC was high in luminal and basal subtypes compared to the claudin low subtype." (PMID 30544991, 2018). "Additional studies are needed to better understand how DRAIC is involved in breast cancer and what molecular pathways are involved." (PMID 30544991, 2018). "Higher expression of DRAIC also predicts poorer overall survival and disease specific survival of breast cancer patients especially in ER positive subtypes." (PMID 30544991, 2018). "Furthermore, the tumor-suppressive mechanisms of DRAIC have been reported in glioblastoma, gastric adenocarcinoma, retinoblastoma, and triple-negative/basal subtype of breast carcinoma." (PMID 38075206, 2024). "And in breast cancer cell lines, lncRNA DRAIC was up-regulated by FOXP3 and promoted cell migration and invasion via the miR-432-5p/SLBP axis.Moreover, lncRNA DRAIC improved esophageal cancer Eca-109 and EC9706 cell invasion through binding to miR-149-5p, which regulated NFIB levels." (PMID 35992823, 2022). "Finally, DRAIC expression in breast cancer was negatively correlated with immune cell infiltration." (PMID 30544991, 2018). "In addition, expression analysis of DRAIC in more than 100 cell lines showed that DRAIC expression is high in luminal and basal subtypes compared to claudin low subtype, suggesting a prognostic value of DRAIC expression in breast cancer." (PMID 30544991, 2018). "We found DRAIC expression was higher in late stage tumors compared to early stages and higher expression of DRAIC is detected in lymph node positive patients compared to lymph node negative patients, indicating DRAIC may be involved also in the metastatic progression of breast cancer." (PMID 30544991, 2018). "Finally, DRAIC is investigated in TIMER and interestingly its expression predicts immune cell infiltration levels in breast cancer." (PMID 30544991, 2018).
breast carcinoma (continued). "Further studies are needed to investigate whether or not DRAIC really participates in immune responses of breast cancer patients and if it acts through cooperation with ER signaling (or HER2 signaling) or not." (PMID 30544991, 2018).
nasopharyngeal carcinoma (5 papers, 2020 to 2022). A carcinoma arising from the nasopharyngeal epithelium. "In nasopharyngeal carcinoma cells, lncRNA DRAIC boosted cell migration and invasion through its interaction with miR-122 and the consequent increase of SATB1 levels." (PMID 35992823, 2022). "lncRNA DRAIC was highly expressed in nasopharyngeal carcinoma cell lines CNE-1 and C666-1 as well as in 32 biopsy tissues." (PMID 35992823, 2022). "Functional assays revealed that DRAIC acts as a miR-122 sponge to facilitate nasopharyngeal carcinoma cell proliferation, migration, and invasion via regulating SATB homeobox 1 (SATB1)." (PMID 34471485, 2021). "Levels of DRAIC expression were related to the clinical stages of nasopharyngeal carcinoma patients." (PMID 34471485, 2021). "In nasopharyngeal carcinoma studies, it was found that DRAIC can sponge miR-122 to promote the expression of SATB1, thus promoting the proliferation, migration, and invasion of nasopharyngeal carcinoma cells." (PMID 34306024, 2021).
gastric cancer (4 papers, 2020 to 2022). A primary or metastatic malignant neoplasm involving the stomach. "In gastric cancer, lncRNA DRAIC has also been indicated to inhibit the proliferation of SGC-7901, HGC-27, and MKN45 cells by binding to UCHL5 and accelerating the ubiquitination of NFRKB." (PMID 35992823, 2022). "The expression of lncRNA DRAIC was downregulated according to tumor progression in 67 primary gastric cancer patients who were submitted to surgical resection as well as in HGC-27, SGC-7901, BGC-823, AGS and MKN45 cell lines." (PMID 35992823, 2022). "For example, it was found in gastric cancer cells that DRAIC can promote the degradation of NFRKB and inhibit the proliferation and metastasis of gastric cancer cells by blocking NFRKB de-ubiquitination mediated by UCHL5." (PMID 34306024, 2021). "lncRNA DRAIC also hindered cell metastasis through its interaction with UCHL5 and repression of NFRKB deubiquitination in gastric cancer." (PMID 35992823, 2022). "DRAIC, a kind of lncRNA whose coding gene location is on 15q23 chromatin, has been found to be weakly expressed in a variety of malignant tumors and acts as a suppressor, but its characteristics and role in gastric cancer (GC) remain to be elucidated." (PMID 32351584, 2020). "Furthermore, we observed that the expression of DRAIC decreased with the progression of gastric cancer, while the low expression of DRAIC and high expression of NFRKB were extremely adverse for the prognosis of GC patients." (PMID 32351584, 2020).
glioma (4 papers, 2021 to 2024). A benign or malignant brain and spinal cord tumor that arises from glial cells (astrocytes, oligodendrocytes, ependymal cells). "Survival analysis has indicated that a high lncRNA DRAIC expression was associated with a remarkably favorable overall survival and progression-free survival of lower-grade glioma patients who had been submitted to radiotherapy." (PMID 35992823, 2022). "Additionally, overexpression of XIST reduced radiosensitivity, while high expression of DRAIC was associated with a better prognosis of radiotherapy in low-grade glioma." (PMID 34322395, 2021). "For example, lncRNA DRAIC expression was demonstrated to predict patient response to radiosensitivity in lower-grade glioma." (PMID 35992823, 2022). "lncRNA DRAIC has been shown to be downregulated in glioma tissues and cell lines (U251, A172, U87, and U373 cells)." (PMID 35992823, 2022). "In glioma, lncRNA DRAIC has been demonstrated to suppress the proliferation of U251 cells by targeting miR-18a-3p." (PMID 35992823, 2022). "In glioma, a TGF‐β signaling‐related 15‐lncRNA signature was constructed, including AC010173.1, HOXA‐AS2, AC074286.1, AL592424.1, DRAIC, HOXC13‐AS, AC007938.1, AC010729.1, AC013472.3, AC093895.1, AC131097.4, AL606970.4, HOXC‐AS1, AGAP2‐AS1, and AC002456.1." (PMID 37850692, 2024). "In human glioma samples, both SET7/9 and lncRNA DRAIC were down-regulated compared with adjacent non-cancerous normal tissues." (PMID 35069908, 2022).
colorectal cancer (3 papers, 2018 to 2024). A primary or metastatic malignant neoplasm that affects the colon or rectum. "DRAIC is a suppressor in gastric and colorectal cancer cells." (PMID 37850692, 2024).
retinoblastoma (3 papers, 2019 to 2022). A malignant tumor that originates in the nuclear layer of the retina. "A recent a study revealed that lncRNA DRAIC was dysregulated in retinoblastoma Y79 cells and 7 retinoblastoma tissues." (PMID 35992823, 2022). "Meanwhile, RNA sequencing (RNA-seq) identified strong down-regulation of DRAIC in retinoblastoma compared with that in normal retina, and restoring DRAIC significantly slowed the growth of the Y79 retinoblastoma cell line." (PMID 32351584, 2020). "We next tested how DRAIC over-expression contributed to the growth of Retinoblastoma cells." (PMID 31058073, 2019).
cholangiocarcinoma (2 papers, 2022 to 2024). A carcinoma that arises from the intrahepatic biliary tree (intrahepatic cholangiocarcinoma) or from the junction, or adjacent to the junction, of the right and left hepatic ducts (hilar cholangiocarcinoma). "In contrast, lower DRAIC expression was observed in cholangiocarcinoma (CHOL), colon adenocarcinoma (COAD), glioblastoma multiforme (GMB), kidney chromophobe (KICH), kidney renal papillary cell carcinoma (KIRP), LUSC, and rectum adenocarcinoma (READ), compared to normal tissues." (PMID 39410631, 2024).
esophageal cancer (2 papers, 2021 to 2022). A primary or metastatic malignant neoplasm involving the esophagus. "Similarly, lncRNA DRAIC led to cell proliferation in esophageal cancer Eca-109 and EC9706 cells through the miR-149-5p/NFIB axis." (PMID 35992823, 2022). "Similarly, lncRNA DRAIC was found to inhibit cell autophagy in esophageal cancer Eca-109 and EC9706 cells acting as ceRNAs to modulate the expression of NFIB by quenching miR-149-5p." (PMID 35992823, 2022).
lung adenocarcinoma (2 papers, 2024). A carcinoma that arises from the lung and is characterized by the presence of malignant glandular epithelial cells. "DRAIC is a migration inhibitor that has been linked with lung adenocarcinoma progression; however, its mechanisms remain to be studied." (PMID 39410631, 2024). "Conversely, pro-oncogenic functions of DRAIC have been demonstrated in nasopharyngeal carcinoma and lung adenocarcinoma." (PMID 38075206, 2024). "Conversely, DRAIC was moderately to highly expressed in some cancer tissues, including prostate adenocarcinoma, invasive ductal carcinoma of the breast, neuroendocrine carcinoma of the esophagus, lung adenocarcinoma, and small cell lung carcinoma." (PMID 38075206, 2024).
lymph node metastasis (2 papers, 2018 to 2022). "Abnormal expression levels of DRAIC have also been associated with clinicopathological features of patients, such as lymph node metastasis, neoplasm stage, overall survival and progression-free survival." (PMID 35992823, 2022). "A high lncRNA DRAIC level was significantly associated with lymph node metastasis, while the downregulation of DRAIC inhibited cell proliferation and metastasis in HGC-27, MKN45, and SGC-7901 cells." (PMID 35992823, 2022). "Moreover, lncRNA DRAIC exhibited a significant association with patient clinicopathological characteristics, especially immune cell infiltration, tumor stage, lymph node metastasis, overall survival and progression-free survival." (PMID 35992823, 2022). "Detailed analyses revealed high DRAIC expression to be correlated to tumor stages and lymph node metastasis of the patients." (PMID 30544991, 2018).
colon cancer (1 paper, 2021). "Furthermore, the expression levels of these lncRNAs were compared between tumor and normal tissue, indicating AL353747.2, AC129492.1, AP003555.1 up-regulated, while DRAIC down-regulated in colon cancer than normal tissue." (PMID 34163531, 2021).
invasive breast carcinoma (1 paper, 2018). A carcinoma that infiltrates the breast parenchyma. "In the present study, we investigated DRAIC expression in 828 invasive breast carcinoma samples and 105 normal samples from The Cancer Genome Atlas (TCGA) and confirmed DRAIC expression was higher in tumor tissues than normal tissues." (PMID 30544991, 2018).
prostate adenocarcinoma (1 paper, 2024). "We demonstrated that DRAIC had tumor-suppressive effects and its high expression was a good prognostic indicator in patients with prostate adenocarcinoma." (PMID 38075206, 2024).